IL15RA (interleukin 15 receptor subunit alpha)
Diseases named in the same sentence as IL15RA in open-access papers (continued):
Sharing a sentence is not in itself a finding about the gene and the disease.
mastitis (2 papers, 2019 to 2025). Inflammation of breast tissue during lactation or postpartum due to an obstructed duct or infection. "Goats’ resistance to gastrointestinal illnesses and mastitis was found to be influenced by the IL15RA gene." (PMID 40559821, 2025).
osteoarthritis (2 papers, 2012 to 2020). A noninflammatory degenerative joint disease occurring chiefly in older persons, characterized by degeneration of the articular cartilage, hypertrophy of bone at the margins and changes in the synovial membrane. "Soluble IL-15Rα was quantified by a newly developed enzyme-linked immunosorbent assay (ELISA) in samples of synovial fluid from patients with RA and osteoarthritis (OA)." (PMID 22888423, 2012).
prostate carcinoma (2 papers, 2015 to 2021). A carcinoma that arises from epithelial cells of the prostate gland. "Co-expression of IL-15 and membrane-associated IL-15Rα by an adenovirus system exerted stronger antitumor effects than IL-15 alone against murine breast and prostate cancer." (PMID 34439192, 2021).
rheumatoid arthritis (2 papers, 2012 to 2024). A chronic, systemic autoimmune disorder characterized by inflammation in the synovial membranes and articular surfaces. "Increased levels of sCD215 (IL-15RA) have been reported in synovial fluid of patients with rheumatoid arthritis." (PMID 39206195, 2024).
type 2 diabetes (2 papers, 2024 to 2025). "IL-15RA was identified as one of 17 proteins involved in 10-year risk of end-stage renal disease in two large U.S. cohorts of individuals with type 2 diabetes." (PMID 38919625, 2024). "Four biomarkers (CDCP1, IL-15RA, MIP-1α, PD-L1) showed inverse associations with CES-D changes in people with type 1 diabetes and positive associations with CES-D changes in people with type 2 diabetes." (PMID 40624224, 2025).
acute myeloid leukemia (1 paper, 2025). Acute myeloid leukemia (AML) is a group of neoplasms arising from precursor cells committed to the myeloid cell-line differentiation. "For example, co-expression of IL-15/IL-15Rα and CD80 in syngeneic acute myeloid leukemia (AML) vaccines generated potent, durable anti-leukemic immunity, yielding 50% overall survival in murine models." (PMID 41196843, 2025).
acute pancreatitis (1 paper, 2024). An acute inflammatory process that leads to necrosis of the pancreatic parenchyma. "Additionally, we have discovered three inflammatory proteins that are also associated with the occurrence of acute pancreatitis, namely interleukin-15 receptor subunit alpha (IL-15RA), monocyte chemoattractant protein-4 (CCL13), and tumor necrosis factor receptor superfamily member 9 (TNFRSF9)." (PMID 38881734, 2024). "We revealed that IL-15RA plays a mediating role in how genus.Coprococcus3 influences the development of acute pancreatitis." (PMID 38881734, 2024). "Our two-step MR analysis, identified IL-15RA as a crucial intermediate factor influencing the relationship between genus.Coprococcus3 and acute pancreatitis." (PMID 38881734, 2024). "Our results support the idea that genus.Coprococcus3 promotes the occurrence of acute pancreatitis through IL-15RA." (PMID 38881734, 2024). "Among these, genetically predicted IL-15RA, monocyte chemoattractant protein-4 (CCL13), and tumor necrosis factor receptor superfamily member 9 (TNFRSF9) showed a significant positive correlation with the occurrence of acute pancreatitis." (PMID 38881734, 2024).
atherosclerosis (1 paper, 2017). A disease characterized by the build-up of fatty material and calcium deposition in the arterial wall resulting in partial or complete occlusion of the arterial lumen. "Surprisingly, some markers of atherosclerosis (fractalkine/CX3CL1, CCL8, M-CSF, HGF), T-cell development/activation (CD40L, IL-7, CCL25, IL-2RB, IL-15RA, CD6) and angiogenesis (VEGF-A) were significantly increased only in AD." (PMID 28821884, 2017).
autoimmune type 1 diabetes (1 paper, 2021). Autoimmune disease wherein the body's own immune system attacks and destroys the cells within the pancreas that produce insulin. "We have shown that the pathogenic potential of IL-15 in autoimmune type 1 diabetes (T1D) does not require IL-15Rα." (PMID 34956227, 2021).
Autoimmunity (1 paper, 2012). The occurrence of an immune reaction against the organism's own cells or tissues. "Thus, IL-15/IL-15Rα activates the JAK1/JAK3 and STAT3/STAT5 pathways to induce proliferation of T and NK cells, and this mechanism could limit exposure to circulating IL-15, that contributeS to the risk of autoimmunity." (PMID 22888423, 2012).
cerebral malaria (1 paper, 2020). A sequestration of Plasmodium falciparum in the brain, which can cause coma and/or seizures. "IL-15/IL-15Rα-Fc complexes (IL15C) have also been shown to expand CD8+ T cell, DN T cell and NK cell populations, and to protect mice against cerebral malaria via the induction of IL-10-producing NK cells." (PMID 32753607, 2020).
cervical carcinoma (1 paper, 2013). A carcinoma arising from either the exocervical squamous epithelium or the endocervical glandular epithelium. "The effect of ectopic expression of SORBS2, TLR3, CYP4V2, FBXO18, IL15RA, WDR37 and DIP2C on the cell phenotype, in particular senescence, was investigated in primary cells, HPV-immortalized cells and cervical carcinoma cells." (PMID 24165198, 2013).
chordoma (1 paper, 2024). Chordomas are rare malignant tumors arising from embryonic remnants of the notochord in axial skeleton. "One additional way to augment the NK and T cell coordinated response against CSCs, particularly in the setting of increased CSC NK ligand expression, could be to employ N803, an interleukin (IL)-15/IL-15-Rα superagonist (N803) previously shown by our group to enhance the killing of chordoma CSCs15." (PMID 38741774, 2024).
colorectal tumor (1 paper, 2025). "Overall, plant-produced Pembrolizumab-IL-15Rα-IL-15 fusion protein showed effective anti-tumor activity in mouse models induced with colorectal tumor." (PMID 39808627, 2025).
fibrosis (1 paper, 2021). the formation of excess fibrous connective tissue in an organ or tissue in a reparative or reactive process. "Since IL-15 or IL-15/IL-15Rα treatments restrained UUO-fibrosis, we performed a semi-quantitative analysis on the cells infiltrating the kidney cortex during UUO by immunostaining using T lymphocytes (CD3) and macrophages (F4/80) markers." (PMID 34769128, 2021). "IL-15/IL-15Rα-treated UUO-kidneys presented a 22% (p < 0.05) and 40% reduction (p < 0.01, n = 7 per group) in collagen accumulation (6.48 ± 0.60% of fibrosis area) compared with IL-15-treated mice (8.3 ± 0.73% of fibrosis area) and vehicle-treated mice (10.71 ± 1.13% of fibrosis area), respectively." (PMID 34769128, 2021).
glaucoma (1 paper, 2022). Increased pressure in the eyeball due to obstruction of the outflow of aqueous humor. "Finally, of further interest is the identification of cell–cell interactions involving ANGPT1-TEK, ICAM1 and IL15RA which were previously attributed to glaucoma and uveitis, respectively." (PMID 36163311, 2022).
head and neck cancer (1 paper, 2025). A primary or metastatic malignant neoplasm affecting the head and neck. "The overexpression of IL15Rα has been reported in head and neck cancer and triple-negative breast cancer." (PMID 40886193, 2025).
Hypertension (1 paper, 2021). The presence of chronic increased pressure in the systemic arterial system. "Inflammation plays an important role in regulating BP and hypertension, so IL‐15 or IL‐15Rα could also have effects on BP and hypertension." (PMID 34586716, 2021).
influenza infection (1 paper, 2012). "In our studies, IL-15Rα was only expressed on a relatively low proportion of NK cells in the lung airways of influenza-infected animals." (PMID 22624047, 2012). "This biased expression of CD122/132 receptor chains over IL-15Rα and enhanced IL-15 levels following influenza infection, indicate that NK cells accumulating at the site of influenza infection are capable of responding to locally produced IL-15 via the trans-presentation pathway." (PMID 22624047, 2012).
Listeria infection (1 paper, 2021). "As depletion of IFNγ in infected Il15ra-/- mice rendered them susceptible to low-dose Listeria infection, it is possible that the DCs are a potential source of early IFNγ in the spleens of Il15ra-/- mice." (PMID 34956227, 2021). "The findings of the present study substantiate this notion by demonstrating that IL-15 can elicit, independently of IL-15Rα, innate immune responses following Listeria infection that involve early IFNγ production necessary for pathogen control by sources other than NK cells." (PMID 34956227, 2021). "In this work, we compared the requirement of IL-15 and IL-15Rα in controlling Listeria monocytogenes infection and determined that IL-15 signaling independent of IL-15Rα is critical for the induction of IFNγ and bacterial clearance." (PMID 34956227, 2021). "Here, we compared the ability of mice lacking IL-15 (no signaling) or IL-15Rα (partial/distinct signaling) to control Listeria monocytogenes infection." (PMID 34956227, 2021).
liver fibrosis (1 paper, 2024). "Our findings reveal that IL-15 exerts a profibrogenic role in liver fibrosis induced by carbon tetrachloride (CCl4) and its pathogenic effects are largely dependent on IL-15Rα-mediated trans-presentation of IL-15." (PMID 38919611, 2024). "Even though the loss of IL-15 or IL-15Rα diminished CCl4-induced liver fibrosis, this reduction was more pronounced in Il15ra–/– mice than in Il15–/– mice." (PMID 38919611, 2024). "As myeloid cells are key players in liver fibrosis and IL-15 signaling can occur independently of IL-15Rα, we investigated the requirement of IL-15 and IL-15Rα in liver fibrosis." (PMID 38919611, 2024). "In conclusion, our findings show that IL-15 signaling via IL-15Rα is strongly pro-inflammatory and profibrogenic during liver fibrosis." (PMID 38919611, 2024). "In the present work, we used both Il15–/– and Il15ra–/– mice to understand the role of IL-15 in chemical induced liver fibrosis and the requirement for IL-15Rα in mediating IL-15 signaling during liver fibrosis." (PMID 38919611, 2024). "The increased fibrosis in CCl4-treated Il15ra–/– mice reported in an earlier study stands in stark contrast to our fining of reduced liver fibrosis in our study." (PMID 38919611, 2024). "We induced liver fibrosis in Il15–/–, Il15ra–/– and wildtype C57BL/6 mice by the administration of carbon tetrachloride (CCl4)." (PMID 38919611, 2024). "In this study, we show that IL-15 promotes pathogenesis of liver fibrosis through IL-15Rα-dependent pro-inflammatory macrophage recruitment." (PMID 38919611, 2024). "Both Il15–/– and Il15ra–/– mice developed markedly reduced liver fibrosis compared to wildtype control mice, as revealed by reduced collagen deposition and myofibroblast content." (PMID 38919611, 2024). "Hence, we tested liver fibrosis development in female Il15–/– and Il15ra–/– mice following CCl4 treatment." (PMID 38919611, 2024). "However, as we observed similarly reduced liver fibrosis both Il15–/– and Il15ra–/– mice under the same experimental settings, our findings strongly support the profibrogenic role of IL-15 signaling in hepatic fibrogenesis." (PMID 38919611, 2024). "As myeloid cells play a key role in liver fibrosis and IL-15Rα-independent IL-15 signaling impacts macrophage functions, we examined macrophage infiltration into the livers of CCl4-treated Il15–/–, Il15ra–/–and wildtype mice." (PMID 38919611, 2024). "However, increased liver fibrosis has been reported in mice lacking IL-15 receptor alpha chain (IL-15Rα), suggesting an anti-fibrogenic role for IL-15." (PMID 38919611, 2024). "However, the paucity of NK cells did not result in increased liver fibrosis CCl4-treated Il15–/– and Il15ra–/– mice in our study." (PMID 38919611, 2024). "Notably, CCl4-treated Il15ra–/– mice showed even less staining of COL1A1 and CD45+ cell infiltration compared to Il15–/– mice, clearly indicating that IL-15 signaling via IL-15Rα-dependent trans-presentation promotes liver fibrosis via promoting inflammatory cell recruitment." (PMID 38919611, 2024).
lymphopenia (1 paper, 2016). Reduction in the number of lymphocytes. "It is well-known that irradiation removes the sinks for homeostasis cytokines such as IL-7 and IL-15 leading to IL-7 and IL-15 increase in lymphopenia, and induces radiation-sensitive hematopoietic cell apoptosis, leading to releasing its IL-15Rα and subsequent formation of IL-15/IL-15Rα complexes." (PMID 27158441, 2016).
metabolic syndrome (1 paper, 2014). A cluster of metabolic risk factors for CARDIOVASCULAR DISEASES and TYPE 2 DIABETES MELLITUS. "Furthermore, several studies reported that there were genetic associations of IL15RA gene polymorphisms with bone volume, muscle strength and volume, and metabolic syndrome." (PMID 25387549, 2014).
metastatic melanoma (1 paper, 2023). A melanoma that has spread from its primary site to another anatomic site. "Our data on metastatic melanoma patients differ from previously published data reporting high plasmatic levels of the sIL-15/IL-15Rα complex in all eight metastatic melanoma patients analyzed." (PMID 37334356, 2023). "detected high levels of sIL-15/IL-15Rα in the sera of eight lympho-depleted metastatic melanoma patients." (PMID 37334356, 2023). "The presence of the soluble complex (sIL-15/IL-15Rα) in the plasma of metastatic melanoma patients was detected using an ELISA assay." (PMID 37334356, 2023). "A previous study reported that plasma samples from lympho-depleted metastatic melanoma patients were characterized by high levels of the sIL-15/IL-15Rα complex." (PMID 37334356, 2023). "Therefore, we analyzed, at two different time points (T1 and T2), the presence of plasmatic sIL-15/IL-15Rα complex in 62 non-lympho-depleted metastatic melanoma patients." (PMID 37334356, 2023). "Since NK cells play a major in the control of the metastatic spread, we hypothesized that the detection of high levels of sIL-15/IL-15Rα in the plasma of both lympho-depleted and non-lympho-depleted metastatic melanoma patients could contribute to the exhaustion of NK cells in these patients." (PMID 37334356, 2023).
myeloma (1 paper, 2020). "Chemotherapy induces SASP containing IL15RA and IL-15 in MM and increased expression of IL-15/IL15RA on the membrane of senescent myeloma cells." (PMID 32570952, 2020).
myositis (1 paper, 2015). "IFN-α, another cytokine up-regulated in myositis muscle, induced Il15 and Il15ra mRNA and IL-15/IL-15Rα complex protein to the level similar to those induced by IFN-γ or TNF-α." (PMID 26417430, 2015). "Together, these results indicate that the expression of the IL-15/IL-15Rα complex protein by skeletal muscle cells was undetectable under steady state conditions, while induced by TNF-α, IFN-γ, or IFN-α that associates with Th1 response in myositis." (PMID 26417430, 2015).
nephritis (1 paper, 2019). Inflammation of renal tissue. "Indeed, experiments in IL-15-/- and IL-15Rα-/- mice show that intrarenal IL-15, present both as secreted and membrane-bound, forms (mbIL-15) anchored through the IL-15Rα chain and protects kidney epithelial cells, counteracting apoptosis, and inflammation during nephritis." (PMID 31360169, 2019).
nephropathies (1 paper, 2019). "Interestingly, decrease in intrarenal IL-15 was closely linked to changes in IL-15Rα in several murine experimental nephropathies." (PMID 31360169, 2019).
pancreatitis (1 paper, 2024). Inflammation of the pancreas. "IL-15RA has a mediating effect of 0.018 (95%CI: 0.005 - 0.032), indicating that 4.713% of the effect of genus.Coprococcus3 on pancreatitis was mediated by IL-15RA." (PMID 38881734, 2024).
pneumonia (1 paper, 2025). An acute, acute and chronic, or chronic inflammation focally or diffusely affecting the lung parenchyma, caused by an infection in one or both of the lungs (by bacteria, viruses, fungi, or mycoplasma.). "Using PCR-DNA sequence verdicts, the TLR2 (354 bp), CLEC4E (443 bp), PTX3 (363 bp), CXCL8 (300 bp), SOCS3 (480 bp) and IL15RA (378 bp) genes were found to have different SNPs in the amplified DNA bases linked to pneumonia." (PMID 40559821, 2025). "Gene expression analysis revealed significant upregulation of immune-related markers (TLR2, CLEC4E, PTX3, CXCL8, IL15RA) and notable SNP variations associated with pneumonia susceptibility." (PMID 40559821, 2025). "The genes TLR2, CLEC4E, PTX3, CXCL8, and IL15RA exhibited significantly higher expression levels in pneumonia-affected ewes compared to healthy controls." (PMID 40559821, 2025). "This study used a PCR-DNA sequencing technique to characterize the immunological (TLR2, CLEC4E, PTX3, CXCL8, SOCS3 and IL15RA) genes in ewes with pneumonia and healthy ewes." (PMID 40559821, 2025).
psychosis (1 paper, 2020). "Immunological factors have been identified as one of the multiple causes of psychosis, and neurological symptoms have been described in IL15Rα knockout (KO) mice." (PMID 33613171, 2020). "Lipid biosynthesis and metabolism in the central nervous system (CNS) should be investigated to provide insights into the effect of IL15Rα on psychosis in this murine model." (PMID 33613171, 2020).
renal carcinoma (1 paper, 2012). A carcinoma arising from the epithelium of the renal parenchyma or the renal pelvis. "Moreover, IL-15 has been found to participate in the development of solid tumors notably, in renal carcinoma where, stimulation of the membrane-bound IL-15 by soluble IL-15Rα chain favors epithelial to mesenchymal transition." (PMID 22363690, 2012).
Sepsis (1 paper, 2023). Sepsis is defined as life-threatening organ dysfunction caused by a dysregulated host response to infection. "The differences observed between these studies are not entirely clear because of the differences in mouse age, dosage, or delivery routes of rIL-15/IL-15Rα complex and models of sepsis." (PMID 37212786, 2023).
severe combined immunodeficiency (1 paper, 2023). Severe combined immunodeficiency (SCID) comprises a group of rare monogenic primary immunodeficiency disorders characterized by a lack of functional peripheral T lymphocytes resulting in early-onset severe respiratory infections and failure to thrive. "In the spontaneous T-ALL model that we reported previously, loss of IL-15 or IL-15Rα in NOD mice with severe combined immunodeficiency (NOD.Scid) resulted in T-ALL development in all mice by 8 months of age, indicating a crucial role for IL-15 signaling in preventing leukemogenesis." (PMID 36765626, 2023).
spondylolisthesis (1 paper, 2026). A condition in which there is forward displacement of a vertebral bone over the on below it. "IP MR identified risk-increasing associations for LSS (4E-BP1 and interleukin-4), spondylolisthesis (CXCL1, CXCL5, FGF-5, IL-15RA, and IL-4) and IDD (IL-20RA and IL-6), while IL-18 showed a protective association with IDD that remained robust after multiple-testing correction." (PMID 42317351, 2026).
T-cell deficiency (1 paper, 2012). "Moreover, the gene transfer procedure partly rescued the NK and memory T-cell deficiency observed in IL-15Rα−/− mice." (PMID 23285013, 2012).
Thrombocytopenia (1 paper, 2022). A reduction in the number of circulating thrombocytes. "Finally, our findings reveal a pattern of MIS-C-defining molecular features (IL15/IL15RA, MIP1α, TNFα, and IL1 pathways) and clinical and laboratory parameters (thrombocytopenia, eosinopenia, and reduced myocardial function)." (PMID 35577777, 2022).